CT47C1 (cancer/testis antigen family 47 member C1)
Gene: Protein-coding gene on chromosome X (119,072,993 to 119,076,765, forward strand). Ensembl gene ENSG00000277535.
Subcellular location (Human Protein Atlas): Nucleoli
Homologues: Orthologues: chimpanzee CT47C1 (93% identical), macaque CT47C1 (77% identical). Paralogues in human: CT47B1 (63% identical), CT47A1 (61% identical), CT47A10 (61% identical), CT47A11 (61% identical), CT47A12 (61% identical), CT47A2 (61% identical), CT47A3 (61% identical), CT47A4 (61% identical), CT47A5 (61% identical), CT47A6 (61% identical), CT47A7 (61% identical), CT47A8 (61% identical), and 1 more.